REST (RE1 silencing transcription factor)
Diseases named in the same sentence as REST in open-access papers (continued):
Sharing a sentence is not in itself a finding about the gene and the disease.
psychiatric disorder (5 papers, 2015 to 2023). A disorder characterized by behavioral and/or psychological abnormalities, often accompanied by physical symptoms. "In the case of at least some psychiatric diseases, the most interesting finding will be a conclusive explanation of the mechanisms of REST action." (PMID 26465007, 2015). "Nonetheless, GWAS has not strongly associated NRSF/REST with psychiatric disorders." (PMID 36216811, 2022). "The hypothesis of this disease is that mental disorders are elicited by the decreased expression of opioid proteins and peptides induced by the upregulation of REST, possibly as a consequence of the decreased expression of the reciprocal miRNAs miR-132, miR-9/9*, and/or miR-124." (PMID 26465007, 2015). "These and other criteria may be ultimately relevant for the investigation of several neurologic and psychiatric diseases, in which knowledge about REST-dependent genes could be ultimately relevant for the diagnosis and prevention, with stimulating perspectives for new forms of therapy." (PMID 26617488, 2015).
genetic disorders (1 paper, 2015). "REST is responsible for silencing neuronal genes in non-neuronal cells, but has also been shown to play a role in some genetic disorders." (PMID 25690042, 2015).
heart (1 paper, 2022). "Persistent expression of REST-regulated genes in α4+ hearts postnatally further implies that in certain pathological situations, the REST protein could also be activated in the adult heart and PGC-1α4 might participate in the induction of neuronal genes that are associated with heart pathologies." (PMID 36230906, 2022).
hereditary neurodegenerative disorder (1 paper, 2009). "The probable decline of miR-9 in AD suggests that its target REST may induce the repression of other neuronal genes and miRNAs (i.e. miR-29a/b, -124, and -132) as reported in the hereditary neurodegenerative disorder, HD." (PMID 19881909, 2009).
REST also shares sentences with these, for which no sentence is quoted: neurodevelopmental disorder (5 papers); sarcoma (4); Ataxia (3); bipolar disorder (3); leukemia (3); Parkinson’s (3); Rett syndrome (3); cardiovascular disease (2); Hearing impairment (2); Neurodegeneration (2); temporal lobe epilepsy (2); acute kidney injury (1); adult T-cell leukemia (1); age (1); alcohol use disorder (1); Alpha-thalassemia (1); Anxiety (1); asthma (1); atrial fibrillation (1); B cell lymphomas (1); brain injury (1); cardiac disease (1); cardiomyopathy (1); cerebral infarct (1); Cerebral ischemia (1); chronic lymphocytic leukemia (1); CNS tumors (1); cognitive disorder (1); colorectal (1); developmental delay (1).
A further 46 diseases each share a sentence with REST in 1 paper.